INS (insulin)
Diseases named in the same sentence as INS in open-access papers (continued):
Sharing a sentence is not in itself a finding about the gene and the disease.
diabetes (continued). "Lastly, fat mass was higher in non-diabetic mice compared to mice with diabetes, not treated with insulin, but similar to diabetic mice treated with insulin." (PMID 40575255, 2025). "There are two main types of diabetes: Type 1 (insulin-dependent) and Type 2 (non-insulin-dependent)." (PMID 40772189, 2025). "He had been diagnosed with diabetes in his home country and had initiated insulin therapy; however, since arriving in Japan, he had not accessed any medical services." (PMID 40381102, 2025). "We performed risk subgroup analyses of patient outcome events according to age, gender, diabetes and non-diabetes, cerebrovascular disease and non-cerebrovascular disease, use insulin and non-use insulin." (PMID 40225324, 2025). "As mentioned, in obesity and diabetes mellitus, anoxic 3T3-L1 adipocytes activate IRE1-mediated UPR to repress the expression of adiponectin, act as an anti-inflammatory and anti-apoptotic agent, and improve insulin sensitivity." (PMID 39791173, 2025). "ARF39, who has had diabetes for 31 years and only recently received an insulin pump, told us how “I still haven’t got used to not giving myself my insulin injection as I feel that something is missing”." (PMID 40565407, 2025). "In general, specific recommendations for most non-insulin diabetes medicines are lacking, with international guidance on glycaemic control in the critically ill focusing on insulin therapy." (PMID 40651878, 2025). "In-hospital and long-term mortality rates were higher in the subgroup of insulin-treated diabetes compared with the subgroup of non-insulin treated diabetes." (PMID 40810069, 2025). "All the patients experienced spontaneous remission of diabetes within 2–6 months of life (median: 4 months) and did not take insulin thereafter." (PMID 41153775, 2025). "The selection of these variables is grounded in the understanding that diabetes arises when insulin secretion fails to meet physiological demands, often due to insulin resistance." (PMID 41012462, 2025). "Furthermore, although these studies showed that insulin self-titration could be equally or more effective than physician-directed titration, their interventions required close medical surveillance which could be challenging for long-term and widespread implementation in diabetes clinics." (PMID 41313169, 2025). "These programmes are often directed toward people with diabetes for whom remission is achievable, that is, shorter diabetes duration, no insulin requirement, lower HbA1c levels." (PMID 40707395, 2025). "A 47-year-old woman developed diabetes mellitus, which was diagnosed as type 1 diabetes mellitus (T1DM) based on a markedly reduced level of endogenous insulin secretion despite being negative for anti-glutamic acid decarboxylase antibody." (PMID 40452801, 2025). "For diabetes, or conditions of cellular nutrient overload relevant to T2DM, mTORC1 is upregulated in β cells while its inhibition prevents β cell death and enhances insulin secretion." (PMID 39996055, 2025). "Type 1 diabetes mellitus (T1DM) is a lifelong autoimmune disorder in which the immune system attacks and destroys the insulin‐producing beta cells in the pancreas, resulting in a permanent reliance on external insulin administration." (PMID 40041785, 2025). "This case highlights the successful management of diabetes in a post-liver transplant patient without the use of insulin or oral antidiabetic agents." (PMID 41141022, 2025). "The aim of the present study was to assess the association of plasma levels of 58 selected sphingolipid species with insulin sensitivity and insulin secretion in adults without diabetes." (PMID 40630937, 2025). "Diabetes mellitus (DM) is a disease where the insulin levels, and thus blood glucose levels, are not properly maintained." (PMID 40284864, 2025).
diabetes (continued). "Despite no significant change in the total daily insulin dose, the proportion of patients on insulin therapy rose from 27% to 39% (P<.001), indicating more targeted and effective diabetes management." (PMID 40934513, 2025). "Diabetes mellitus represents a key cardiometabolic comorbidity of particular interest in patients with inflammatory bowel disease (IBD), given the shared pathways of insulin resistance and systemic inflammation with metabolic dysfunction-associated steatotic liver disease (MASLD)." (PMID 41583302, 2025). "Three had a diagnosis of diabetes before surgery and were treated with insulin and/or metformin, but none were treated with GLP-1 agonists." (PMID 40474966, 2025). "Age, duration of diabetes, serum creatinine levels, and total insulin dose were not significant predictors of hypoglycemia occurrence (p>0.05) (data not shown)." (PMID 41293743, 2025). "Forty adults with type 1 diabetes, and twenty adults without diabetes were studied in a baseline only cross-sectional study assessing insulin resistance using the two-step hyperinsulinemic-euglycemic clamp." (PMID 41285865, 2025). "There were also no changes in insulin or other diabetes medications, nor in medications for lowering blood lipids or regulating body metabolism (thyroxine) during the study." (PMID 40933253, 2025). "Transcriptomic data indicated significant downregulation of islet hormone genes insulin (INS) and glucagon (GCG) but not somatostatin (SST) in PDAC-associated diabetes, consistent with a type 3c diabetes phenotype." (PMID 40244011, 2025). "Individuals were considered insulin sensitive (IS) if lean, not diagnosed with diabetes, no hypertriglyceridemia, and not on lipid-lowering drugs, while individuals with Type 2 diabetes (T2D) were considered insulin resistant (IR)." (PMID 40421243, 2025). "These included advanced age (AOR: 4.32, 95% CI: 0.61–11.21, p = 0.012), duration of diabetes mellitus > 10 years (AOR: 3.60, 95% CI: 1.05–9.82, p = 0.019), insulin therapy (AOR: 3.13, 95% CI: 0.55–11.01, p = 0.009) and the presence of hypertension (AOR: 2.88, 95% CI: 0.75–5.45, p = 0.030)." (PMID 40078898, 2025). "Individuals diagnosed with type 1 diabetes mellitus (T1DM) face challenges due to inadequate or absent insulin secretion, necessitating vigilant monitoring of blood glucose levels (BGL)." (PMID 39869550, 2025). "Key factors linked to poor glycemic control included low socioeconomic status, medication non-adherence, longer diabetes duration, obesity, insulin-based regimens, and limited access to healthcare." (PMID 40385776, 2025). "Regarding the treatment of diabetes, 41.2% used insulin, 38.7% relied on oral hypoglycemic drugs, and 20.1% did not receive medication." (PMID 40408408, 2025). "Previous studies of patients with diabetes and treated with dialysis have shown that 23% are not treated with pharmacotherapy and ≈30% have a haemoglobin A1c <6%, likely due to changes in insulin metabolism that occur in kidney failure." (PMID 38964833, 2025). "Hierarchical diabetes risk stratification: We quantify a stepwise mortality gradient in a CTO cohort, extending from non-diabetic patients to those with non-insulin-dependent and, highest of all, insulin-dependent diabetes." (PMID 40967652, 2025). "Age, gender, diabetes duration, use of oral hypoglycemic agents, glycemic control, and insulin regimen were not related to sleep quality significantly (p > 0.05)." (PMID 40357213, 2025). "First, from a clinical perspective, our data do not includepatients’ medical history such as insulin use, type of diabetes, and duration of diabetes.Second, the database lacks information on important comorbidities and anthropometry." (PMID 40232166, 2025). "Differential diagnosis of hypoglycemia in patients without diabetes includes insulinoma, noninsulinoma pancreatogenous hypoglycemia, postbariatric hypoglycemia, insulin autoimmune hypoglycemia, and insulin secretagogue pathways." (PMID 40727482, 2025).
diabetes (continued). "The most commonly recognized form of naturally occurring diabetes mellitus (NODM) in dogs is similar to type 1 diabetes mellitus (T1DM) in people and is characterized by hypoinsulinemia and a dependence on exogenous insulin administration to maintain euglycemia, mitigate ketosis, and survive." (PMID 39234180, 2024). "In an oxidative stress model, including relevant diabetic and non-diabetic control groups, we tested the effects of insulin-treated diabetes in a novel mouse model of mitochondrial dysfunction." (PMID 38397785, 2024). "Here we show, in β-cells from overweight humans without diabetes and mice fed a high-fat diet for 2 days, insulin exocytosis and secretion are enhanced without increased Ca2+ influx." (PMID 38184650, 2024). "The hallmark of type 1 diabetes mellitus (T1DM) is the autoimmune destruction of beta cells, which leads to their complete loss and, as a result, a severe decrease in or absence of insulin." (PMID 39347125, 2024). "In individuals without diabetes, there is a portal-peripheral insulin gradient indicating clearance of insulin by the liver." (PMID 39595651, 2024). "Type 2 diabetes mellitus (T2DM) is a complex condition with multiple contributing factors, characterized by inadequate insulin production by pancreatic beta cells or resistance to insulin in the target organs." (PMID 39413550, 2024). "In contrast to cardiovascular complications, the incidence of diabetes complications such as retinopathy, nephropathy, and neuropathy was significantly higher among patients on insulin compared to those not on insulin (50.7 % versus 27.5 %; p = 0.005)." (PMID 39295783, 2024). "Supporting an important role for CD69+ activated T cells in diabetes, CD69 expression has been found to be increased in T cells from insulin-stimulated whole blood from T1D patients compared to healthy controls as well as in diabetic compared to nondiabetic T cells from NOD mice." (PMID 38487540, 2024). "However, over time, and after learning more about diabetes, most participants accepted that, while managing the condition was demanding, they could lead a “normal life” if they ate properly, exercised, monitored their blood sugar levels, and regularly injected insulin." (PMID 40401305, 2024). "Additionally, TGF-β2, an exercise-induced adipokine, mediates glucose homeostasis, improves insulin sensitivity, increases FFA uptake and oxidation, and promotes mitochondrial function in response to diabetes." (PMID 38786764, 2024). "Type 2 diabetes mellitus (T2DM) is a chronic metabolic disorder characterized by persistent hyperglycemia due to impaired insulin secretion and resistance to peripheral actions of insulin." (PMID 39410536, 2024). "CKD patients whose diabetes is controlled by non-insulin oral or injectable agents, diet or exercise are not eligible for pancreas transplantation currently in the US based on allocation policy." (PMID 39364120, 2024). "Unlike insulin, glibenclamide, and chlorpropamide, metformin has shown a notable 30% decrease in mortality and complications related to diabetes." (PMID 38558585, 2024). "In both the definition and the validation dataset key markers of insulin‐glucose homeostasis differed between subjects with and without diabetes." (PMID 38169110, 2024). "Exogenously administered insulin is a critical tool in the management of diabetes—in 2021, the Centers for Disease Control and Prevention (CDC) reported that 12.3% of all United States adults with diabetes started using insulin within a year of their diagnosis." (PMID 39458209, 2024). "Additionally, as the findings showed, exercise training has great potential to improve diabetes-related biochemical indices such as FBG, insulin, HOMA-IR, HbA1c, and blood pressure." (PMID 38238647, 2024).
diabetes (continued). "Since insulin resistance was identified in young healthy SA men in the absence of diabetes and is an early marker of endothelial dysfunction and risk of CVD in young adults, plasma insulin and fasting glucose should also be assessed." (PMID 39275227, 2024). "Insulin can be a valuable treatment for hypertriglyceridemia during pregnancy not related to diabetes because it can help to increase the breakdown of triglycerides and reduce fat burning." (PMID 39457565, 2024). "Nonetheless, in later stages of T2DM and in type 1 diabetes mellitus (T1DM), insulin levels markedly decline due to pancreatic damage, resulting in degenerative alterations such as reductions in pancreatic cell numbers and sizes, central region vacancies, and exhaustion of pancreatic ꞵ-cells." (PMID 38890991, 2024). "In addition, we investigated whether the Diabetes Dietary Quality index (DDQ-index) retrieved from this questionnaire was associated with type 2 diabetes-related metabolic risk factors, including measurements of beta cell function and insulin sensitivity (mixed meal- and clamp-derived measurements)." (PMID 39458507, 2024). "Insulin and glucagon were 48% and 29% higher, respectively, in the incident diabetes group compared with the non-diabetes group; however, we found no temporal trends for these biomarkers." (PMID 39078488, 2024). "In support of this, when insulin is infused to healthy individuals without diabetes to levels observed in patients with T1D on insulin treatment, insulin sensitivity decreases." (PMID 39906033, 2024). "In addition, patients with both type 1 and type 2 diabetes with MASLD increase insulin requirements to achieve comparable glycemic control, indicating that diabetic patients with MASLD need more intensive diabetes treatment." (PMID 39470335, 2024). "In particular, there is a lack of sufficient data in patients with type 2 diabetes mellitus treated long-term with high doses of insulin or with significantly deteriorated glycaemic control (or a combination of both factors)." (PMID 38792590, 2024). "In PDAC, the IAPP concentrations were 25.0 ± 8.7 pmol/L in seven patients with diabetes requiring insulin, 31.4 ± 12.6 pmol/L in 11 patients with diabetes not requiring insulin, and 12.2 ± 2.4 pmol/L in 9 patients with normal glucose tolerance." (PMID 39596226, 2024). "Diabetes mellitus, particularly type 2 diabetes mellitus (T2DM), is a common metabolic disorder characterized by mainly the combination of defective insulin secretion by pancreatic β-cells and the inability of insulin-sensitive tissues to respond appropriately to insulin." (PMID 39347127, 2024). "When speaking about the need for more affordable supplies, many participants expressed a desire for equity: “...Individuals with diabetes should not be discriminated against by policies that support insulin pumps for specific age groups and not others." (PMID 38711747, 2024). "This study aimed to compare newly developed diabetes-specific complete smoothie formulas with a standard diabetes-specific nutritional formula (DSNF) regarding their effects on glucose homeostasis, insulin levels, and lipid metabolism in obese type 2 diabetes (T2DM) patients." (PMID 38337679, 2024). "Some studies demonstrate that myriocin ameliorates clinical manifestations of insulin resistance such as peripheral glucose tolerance and upregulates insulin-stimulated Akt phosphorylation, thus preventing clinical transformation to frank T2DM in both genetic and diet-induced models of diabetes." (PMID 39408263, 2024). "Diabetes is characterised by raised blood glucose levels, insulin resistance, a slight or absolute lack of insulin activity, and the development of diabetes-specific pathology in the retina." (PMID 38357071, 2024).
diabetes (continued). "In the ROR analysis of known drugs used in diabetes, rosiglitazone had the highest ROR (44.47), followed by the rosiglitazone-metformin combination (ROR 14.62), pioglitazone (ROR 6.58), metformin (ROR 1.14), and insulin lispro (ROR 0.79)." (PMID 39881876, 2024). "The most common diabetes type is type 2 diabetes (accounting for about 96%), which is usually found in adults and occurs when the body becomes resistant to insulin or does not produce enough insulin." (PMID 39678201, 2024). "Glycemic markers, including postprandial glucose, insulin, and insulin resistance, are strong predictors of morbidity and mortality in individuals with and without diabetes." (PMID 38572086, 2024). "Early and late administration of DMEM did not alter serum glucose and insulin levels compared to the diabetes group." (PMID 39391856, 2024). "In diabetes mellitus, the body either does not produce enough insulin (type 1) or cannot effectively use the insulin it produces (type 2), leading to elevated blood sugar levels." (PMID 39323638, 2024). "There have been significant reductions in the incidence rates of severe hypoglycemia over the past two decades for several reasons, not least the introduction of insulin analogues, improved diabetes technologies, and improved hypoglycemia education." (PMID 38894740, 2024). "Third, the index patient had diabetes with normal peripheral insulin levels, suggesting insulin resistance for which the β cells failed to compensate." (PMID 38775154, 2024). "A key issue is the fear of alcohol consumption due to a lack of knowledge about its impact on diabetes management and insulin regulation." (PMID 38338194, 2024). "When compared with patients without diabetes, the 30-day and 90-day mortality rate was higher in the group with diabetes treated only with insulin (p < 0.001, p = 0.003) and in the group treated only with other antidiabetics (p = 0.002, p = 0.032)." (PMID 38849653, 2024). "TyG has emerged as a novel tool that demonstrates superiority over HOMA-IR in evaluating insulin resistance, particularly in individuals with diabetes undergoing insulin therapy or those lacking functional beta cells." (PMID 39872136, 2024). "The OAD group exhibited a higher incidence of well-controlled diabetes than the insulin group, but the difference was not statistically significant (p = 0.097, log-rank test)." (PMID 38969701, 2024). "Second, there was considerable heterogeneity in patient demographics (e.g., age), duration of diabetes, medical history (e.g., baseline HbA1c), treatment history, and concomitant medications for T2DM (e.g., insulin, metformin, or other glucose-lowering agents) among the included studies." (PMID 38500154, 2024). "To date, counterregulatory hormone and symptom responses to hypoglycaemia have not been directly compared between people with type 1 diabetes and those with insulin-treated type 2 diabetes vis-à-vis controls without diabetes." (PMID 38376580, 2024). "A diabetes-specific awareness evaluation was carried, and the relationship between regular exercise and insulin in short sleepers was observed among participants without have diabetes." (PMID 39469577, 2024). "The crude annual rates of pancreatic cancer were similar among GLP-1RA users and nonusers, but higher among basal insulin users, most probably due to their older age and longer diabetes duration." (PMID 38175642, 2024). "Human milk from mothers with diabetes contains several-fold increased concentrations of insulin, and human milk insulin concentrations are strongly correlated with circulating insulin concentrations also in mothers without diabetes." (PMID 39981021, 2024). "Smart insulin pens, such as the InPen (Medtronic, Dublin, Ireland) and NovoPen 6 (Novo Nordisk, Bagsværd, Denmark), represent a big advancement in diabetes management by integrating technology to improve the accuracy and convenience of insulin administration." (PMID 39006724, 2024).